MAGI2 (membrane associated guanylate kinase, WW and PDZ domain containing 2)
Description:
Seems to act as a scaffold molecule at synaptic junctions by assembling neurotransmitter receptors and cell adhesion proteins (By similarity). Plays a role in nerve growth factor (NGF)-induced recruitment of RAPGEF2 to late endosomes and neurite outgrowth (By similarity). May play a role in regulating activin-mediated signaling in neuronal cells (By similarity). Enhances the ability of PTEN to suppress AKT1 activation. Plays a role in receptor-mediated clathrin-dependent endocytosis which is required for ciliogenesis (By similarity).
Synonyms: AIP-1; MAGI-2; AIP1; KIAA0705; ARIP1; ACVRIP1; NPHS15; SSCAM
Tractability: Antibody: its Gene Ontology location is reachable by antibodies, with high confidence; UniProt places it where antibodies can reach, with medium confidence. PROTAC: its protein half-life has been measured.
Gene: Protein-coding gene on chromosome 7 (78,017,055 to 79,453,667, reverse strand). Ensembl gene ENSG00000187391.
Subcellular location: Cytoplasm; Late endosome; Synapse, synaptosome; Cell membrane; Cytoplasm, cytoskeleton, microtubule organizing center, centrosome; Cell projection, cilium; Cytoplasm, cytoskeleton, microtubule organizing center, centrosome, centriole; Photoreceptor inner segment; Cell projection, cilium, photoreceptor outer segment
Pathways (Reactome):
Cell-Cell communication: Nephrin family interactions
Gene Ontology:
Molecular function: beta-1 adrenergic receptor binding; phosphatase binding; protein binding; signaling receptor complex adaptor activity; SMAD binding; type II activin receptor binding
Biological process: negative regulation of phosphatidylinositol 3-kinase/protein kinase B signal transduction; positive regulation of receptor internalization; cellular response to nerve growth factor stimulus; clathrin-dependent endocytosis; negative regulation of activin receptor signaling pathway; negative regulation of cell migration; negative regulation of cell population proliferation; nerve growth factor signaling pathway; podocyte development; positive regulation of neuron projection development; receptor clustering; signal transduction; SMAD protein signal transduction; Wnt signaling pathway, planar cell polarity pathway
Cellular component: bicellular tight junction; cytoplasm; nucleus; plasma membrane; cell-cell junction; centriole; ciliary base; dendrite; late endosome; perinuclear region of cytoplasm; photoreceptor inner segment; photoreceptor outer segment; postsynaptic density; protein-containing complex; slit diaphragm; synapse; centrosome; cilium
Genetic constraint (gnomAD): Loss-of-function variants: 30 observed, 110.29 expected, observed/expected ratio (o/e) 0.27, 90% interval 0.2 to 0.37. The upper end of that interval is the gene's LOEUF score, 0.37, which puts it in group 1 of 6, group 1 being the genes least tolerant of losing a copy. Missense variants: 1,519 observed, 1,731 expected, observed/expected ratio (o/e) 0.88, 90% interval 0.84 to 0.92. Synonymous variants: 671 observed, 668.55 expected, observed/expected ratio (o/e) 1, 90% interval 0.94 to 1.07.
Gene-disease validity (ClinGen):
ClinGen rates the evidence that MAGI2 causes each of these diseases.
epilepsy (autosomal dominant): Refuted. A brain disorder characterized by episodes of abnormally increased neuronal discharge resulting in transient episodes of sensory or motor neurological dysfunction, or psychic dysfunction.
Homologues: Orthologues: macaque MAGI2 (99% identical), pig MAGI2 (96% identical), rabbit MAGI2 (95% identical), mouse Magi2 (93% identical), rat Magi2 (93% identical), dog MAGI2 (90% identical), chimpanzee MAGI2 (86% identical), guinea pig MAGI2 (80% identical), tropical clawed frog magi2 (79% identical), zebrafish magi2b (61% identical). Paralogues in human: MAGI1 (45% identical), MAGI3 (42% identical), GRIP2 (14% identical), GRIP1 (14% identical), SAV1 (7% identical), MAGIX (7% identical).
Diseases named in the same sentence as MAGI2 in open-access papers:
MAGI2 is named in the same sentence as 84 diseases in open-access papers, as found by Europe PMC text mining. Sharing a sentence is not in itself a finding about the gene and the disease. The quoted sentences say what the papers report.
schizophrenia (13 papers, 2012 to 2024). A major psychotic disorder characterized by abnormalities in the perception or expression of reality. "MAGI2 exhibits a strong association with schizophrenia, it is also involved in celiac disease, bipolar disorder, nephrotic syndrome type 15, and west syndrome." (PMID 39434882, 2024). "In this study, we investigated the association between 4 SNPs within MAGI2 and schizophrenia in the Japanese population." (PMID 22649501, 2012). "We found suggestive evidence for genetic association of common SNPs within MAGI2 locus and schizophrenia in Japanese population." (PMID 22649501, 2012). "Variations in the scaffold protein coding gene MAGUK Inverted 2 (MAGI-2), which may be implicated in postsynaptic density and neurotransmission, have been found in patients with neurological disorders such as schizophrenia." (PMID 38328521, 2023). "Moreover, prior GWAS linked MAGI2 to schizophrenia, evidence further supported by the detection of duplications and variations of this gene in schizophrenic patients." (PMID 35052345, 2021). "In conclusion, although we could not detect strong genetic evidence for association of common variants in MAGI2 and increased schizophrenia risk in a Japanese population, these SNPs may increase risk of cognitive impairment in schizophrenic patients." (PMID 22649501, 2012). "However, several weak association signals (p<0.05) within the MAGI2 locus were detected in the first genome-wide association study of schizophrenia conducted in a Japanese population (JGWAS)." (PMID 22649501, 2012). "In this study, we examined the relationship of SNP variations in MAGI2 and the risk for schizophrenia in a large Japanese case-control sample and also explored potential relationships between variations in MAGI2 and aspects of human cognitive function related to glutamate activity." (PMID 22649501, 2012). "Moreover, we have provided evidence that common SNPs in the MAGI2 gene region increase risk of cognitive impairment in schizophrenia." (PMID 22649501, 2012). "We detected suggestive evidence of associations between MAGI2 and schizophrenia in the joint analysis; however, as the JGWAS dataset was included in the joint analysis, evidence for association might be overestimated." (PMID 22649501, 2012). "Additional proteins with schizophrenia rare variant associations (via the SCHEMA consortium) altered in 22q11.2del neurons included DNM3, MAGI2 and TRIO (downregulated in patient neurons) and HIST1H1E, SRRM2 and ZMYM2 (upregulated in patient neurons)." (PMID 35760976, 2022). "HOMER1, MAGI2, SLC1A3, NRG3 were associated with schizophrenia." (PMID 32993537, 2020). "Variations in MAGI2, a synaptic scaffolding molecule with an essential role in synaptic transmission, are known to be related to epilepsy and cognitive impairment in patients with schizophrenia." (PMID 28427329, 2017). "Some have been associated with neurodevelopmental disorders: schizophrenia (DIXDC1, ARVCF, MAGI2, ZIC2), ADHD (attention deficit/hyperactivity disorder) (TCERG1L), movement disorders (NOL3, TP53INP2), Huntington’s disease (H2AFY2, AGPAT1), Parkinson’s disease (LMX1B), and autism (PLXNA4, WNT2)." (PMID 25748564, 2015). "In conclusion, common variants in MAGI2 selected based on JGWAS findings, may be associated with increased schizophrenia risk in a Japanese population." (PMID 22649501, 2012). "A genetic association study designed to evaluate the association between MAGI2 and cognitive performance or schizophrenia has not been conducted." (PMID 22649501, 2012). "Interestingly, recent copy number variation analyses have identified deletions in gene coding MAGI2 in schizophrenia." (PMID 22649501, 2012).
breast carcinoma (8 papers, 2015 to 2024). "MAGI2 has been previously implicated in regulating the migration and evasion of the breast cancer cells." (PMID 32672418, 2020). "Our findings of MAGI2 mutation in breast carcinoma with high TMB warrant future study to investigate MAGI2’s function in DNA repair pathway and PTEN signaling pathway." (PMID 32393302, 2020). "MAGI2 was reported to act as an anti-tumor in hepatocellular cancer and breast cancer; its down-regulation has been demonstrated in NSCLC." (PMID 34262872, 2021). "Conjointly, exosomal miR‐27a‐3p promotes immune evasion by up‐regulating PD‐L1 via MAGI2/PTEN/PI3K axis in breast cancer." (PMID 32672418, 2020). "In breast cancer, ERS promotes miR‐27a‐3p expression, which then upregulates PD‐L1 through the MAGI2/PTEN/PI3K axis, ultimately contributing to immune evasion by the tumor." (PMID 36999888, 2023). "Previous studies have also shown that miR-27a-3p can target and negatively regulate MAGI2, which inactivates the PI3K/AKT signalling pathway by upregulating PTEN and downregulating PD-L1, thereby promoting immune evasion in breast cancer cells." (PMID 35978806, 2022). "For instance, knockdown of SMYD3 induced apoptosis through G1-phase cell cycle arrest in breast cancer cell line MDA-MB-231, and MAGI2 cooperates with PTEN to inhibit the growth of tumor cells by suppressing the activation of Akt." (PMID 25889623, 2015).
celiac disease (6 papers, 2013 to 2025). An autoimmune genetic disorder with an unknown pattern of inheritance that primarily affects the digestive tract. "It is worth noting that MYO9B, PARD3, and MAGI2 were also reported to be celiac disease susceptibility genes." (PMID 24062746, 2013). "In addition, previous studies indicated that significant associations were found between MAGI2 and celiac disease, IBD, CD, as well as ulcerative colitis (UC)." (PMID 40625359, 2025). "Decreased expression of MAGI3 has also been described to contribute to the pathogenesis of IBD, and genetic variations of the gene MAGI2 have similarly been described in Crohn’s disease, ulcerative colitis, and celiac disease." (PMID 34198584, 2021). "Similar to MYOIXB, PARD3, and MAGI2 variants, the DLG5 R30Q polymorphism has also been reported to be associated with celiac disease, corroborating the concept that a common mechanism, that is breakdown of the intestinal barrier, may exist between celiac disease and IBD." (PMID 24062746, 2013).
epilepsy (6 papers, 2012 to 2025). "The gene overlapping with ENSMUSG00000067798 encodes MAGI2, a kinase enzyme involved in several processes and found to cause epilepsy when disrupted in human infants." (PMID 23185269, 2012). "CACNB4, CLCN2, MAGI2, and SRPX2 variants have all been proposed as causes of epilepsy." (PMID 40492992, 2025).
prostate carcinoma (6 papers, 2019 to 2021). A carcinoma that arises from epithelial cells of the prostate gland. "MAGI2 was proposed as a novel diagnostic marker and suggested as a predictor of tumor recurrence in prostate cancer." (PMID 34198584, 2021). "Knockdown experiments have shown that loss of MAGI2 expression induces AKT phosphorylation; MAGI2 levels are decreased in prostate cancer and correlate with NKX3.1 level." (PMID 31366128, 2019). "The critical role of MAGI2 gene has been implicated in prostate cancer and hepatocellular cancers." (PMID 33579893, 2021). "Whole genome sequencing of seven cases of prostate cancer revealed that, in addition to mutational events occurring in the PTEN gene due to breakpoints, rearrangements disrupting the MAGI2 gene, encoding for a PTEN-interacting protein, have been observed." (PMID 31366128, 2019). "MAGI2 level is decreased during prostate cancer progression and is a predictor of biochemical recurrence." (PMID 31366128, 2019). "As regards MAGI2, conflicting observations have been reported in prostate cancers." (PMID 34503076, 2021). "Some genomic rearrangements of MAGI2 have also been evidenced in melanoma cell lines and prostate cancers leading to in-frame deleted transcript with an unknown biological significance, and to MAGI2 invalidation, respectively." (PMID 34503076, 2021). "MAGI2 has been reported as an independent predictor of recurrence in prostate cancer." (PMID 32672418, 2020). "Additionally, MAGI2 is abnormally expressed in high grade prostatic intraepithelial neoplasia and prostate cancer compared to benign glandular epithelium." (PMID 32393302, 2020).
nephrotic syndrome (5 papers, 2022 to 2025). A collection of symptoms that include severe edema, proteinuria, and hypoalbuminemia; it is indicative of renal dysfunction. "In patients, recessive mutations in the MAGI2 gene lead to a steroid-resistant nephrotic syndrome with a focal and segmental sclerosing (FSGS) histologic phenotype indicating primary podocyte injury." (PMID 40563084, 2025). "Among the upregulated genes, MAGI2 (membrane-associated guanylate kinase, WW, and PDZ domain containing 2) mutation is a cause of the nephrotic syndrome." (PMID 40149392, 2025). "Mutations in the gene encoding MAGI-2 in humans result in nephrotic syndrome, a glomerular pathology where the breakdown of the podocyte intercellular junction and consecutive filtration barrier dysfunction result in loss of protein into the urine." (PMID 35372328, 2022). "In humans, recessive mutations in the MAGI2 gene lead to steroid-resistant nephrotic syndrome." (PMID 40563084, 2025). "In line with that, we found MAGI2 unchanged in MCD but significantly downregulated in collapsing FSGS in a publicly available transcriptomic dataset of isolated glomeruli of a nephrotic syndrome patient cohort." (PMID 40563084, 2025).
depression (4 papers, 2019 to 2025). "Altogether, both variant-level, gene-level and functional level evidence strongly suggest MAGI2 as a novel risk gene for depression." (PMID 36685848, 2022). "Gene prioritization analysis based on already known depression risk genes indicated MAGI2 (S-SCAM) as the most probable gene from the locus and potential susceptibility gene for the disease." (PMID 36685848, 2022). "Brain and gut expression patterns were the main features highlighting functional relatedness of MAGI2 to the previously known depression risk genes." (PMID 36685848, 2022). "The role of MAGI2 in depression has been linked to disruptions in the gut–brain axis." (PMID 39703455, 2024). "It should be noted, that while several independent methods successfully in silico validate the role of MAGI2, we were unable to replicate genetic association for the leading variant in the MAGI2 locus, therefore the role of rs521851 in depression should be interpreted with caution." (PMID 36685848, 2022). "The novel candidate gene identified in the study—MAGI2, is an illustration of how genetic susceptibilities for depression could be associated with systemic symptoms related to psychiatric traits." (PMID 36685848, 2022). "Here, we present a depression GWAS study of a cohort of Russian descent individuals identifying MAGI2 as a potential susceptibility gene that could link inherited risks of depression and gastrointestinal conditions, associated with changes in gut permeability." (PMID 36685848, 2022). "An association between the MAGI2 (S-SCAM) intron variant rs521851 and depression symptoms, as measured by the depression subscale of the Hospital Anxiety and Depression Scale (HADS-D), has been recently reported." (PMID 39703455, 2024). "MAGI2 can affect psychological symptoms of depression, measured by HADS-D scale both indirectly, through its effect on immune homeostasis associated with the gut–brain axis and directly as a synaptic scaffolding molecule." (PMID 39703455, 2024). "MAGI2 is also interacting with a range of receptors for which multiple lines of evidence suggest involvement in development of both depression as well as of IBS and/or IBD symptoms." (PMID 36685848, 2022). "This indicates that MAGI2 could be one of the genes involved in the processes driving comorbidity between depression and diseases of the gut-brain axis, such as IBS." (PMID 36685848, 2022). "Expression patterns and functional profile of MAGI2 suggest that it could be involved in the development of both depression phenotypes and gastrointestinal conditions, such as IBS and IBD." (PMID 36685848, 2022).
Alzheimer disease (3 papers, 2020 to 2022). A progressive, neurodegenerative disease characterized by loss of function and death of nerve cells in several areas of the brain leading to loss of cognitive function such as memory and language. "In particular, MAGI2 has been associated with Alzheimer′s Disease (AD) and it has been proposed as a candidate transcriptomic biomarker of AD." (PMID 35052345, 2021). "MAGI2 is a candidate gene associated with multiple phenotypes, as demonstrated by Alzheimer’s Disease Neuroimaging Initiative genetic studies." (PMID 32816243, 2020). "Recently, it has been shown that the MAGI-2 differential gene in elderly patients with Alzheimer’s disease is expected to be an important screening marker as a differential gene for Alzheimer’s disease in the elderly, but whether MAGI-2 is involved in the development of POD is not clear." (PMID 35294925, 2022).
autism (3 papers, 2015 to 2019). Persistent deficits in social interaction and communication and interaction as well as a markedly restricted repertoire of activity and interest as well as repetitive patterns of behavior. "From the total set of genes constituting the NBC, 233 candidates occur in at least 5 sibling conditions, 74 are present in 7 or more siblings, 29 in 8 or more, 13 in 9 autism siblings, 3 in 10 autism sibling disorders (MAGI2, NR3C1, SLC1A2) and one (SLC1A2) present in 12 siblings." (PMID 28427329, 2017).
Cognitive impairment (3 papers, 2012 to 2022). Abnormal cognition is characterized by deficits in thinking, reasoning, or remembering. "Our results thus extend findings for the role for MAGI2 in serious neuropsychiatric conditions by suggesting that a mutation in MAGI2 may be present at the level of brain information processing implicated in cognitive impairment." (PMID 22649501, 2012).